BRCA1 (BRCA1 DNA repair associated)
Diseases named in the same sentence as BRCA1 in open-access papers (continued):
Sharing a sentence is not in itself a finding about the gene and the disease.
tumor (continued). "It highlights the need for timely access to genomic testing including tumour and germline BRCA1/2 mutation assessment and HRD assays to guide PARP inhibitor selection." (PMID 35735457, 2022). "Subsequent studies led to the characterisation of a second G4 ligand, CX‐5461, which is also specifically toxic to BRCA1/2‐deficient cells and tumours." (PMID 35107878, 2022). "In mouse models with BRCA1-deficient tumors, prolonged treatments with PARPi revealed that loss of 53BP1 expression in tumor cells can account for this resistance." (PMID 36553657, 2022). "Recently, PARPis, which target the key enzyme PARP in DNA damage response, have demonstrated potent antitumor effects due to synthetic lethality exerted on tumor cells deficient in DNA damage repair, most remarkably those with BRCA1/2 mutations." (PMID 36324587, 2022). "While our study demonstrates TGFβR2 induces malignant phenotypes in p18/BRCA1-deficient tumors, other studies show opposing roles in tumor suppression or tumor promotion." (PMID 35236825, 2022). "PARP inhibitors impair SSB repair to cause tumor cells to transform into DNA DSBs in the S phase, which leads to cell death due to mitotic catastrophe or apoptosis in tumors with BRCA1 and BRCA2 mutations as well as an HR deficiency." (PMID 35480096, 2022). "Another limitation what we found was the correlation between BRCAness and BRCA1 mutation of the tumor where we are unable to distinguish germline from somatic mutation." (PMID 36371386, 2022). "Myriad myChoice® CDx detects the defects in homologous recombination repair and BRCA1/2 mutations by evaluating genomic instability in genomic DNA extracted from tumor tissues." (PMID 35191009, 2022). "Tumor cells that are defective in HR due to loss of BRCA1 or BRCA2 use alternative error-prone pathways that lead to fragmentation of the genome and ultimately result in cell death." (PMID 35203410, 2022). "Allele frequency evaluated in tumor tissue ranged from 6.4% to 89.8%, with 6.4% to 89.8% for germline BRCA1/2 wild-type patients compared to 49.9% to 88.8% for germline BRCA1/2 mutated patients." (PMID 36143252, 2022). "The aim of the study was to determine PARP-1 expression and BRCA1 mutations in circulating tumor cells (CTCs) of BC patients." (PMID 35406503, 2022). "Both types of replication barriers induce DNA damage, which is particularly toxic to BRCA1/2‐deficient cells and tumours." (PMID 35107878, 2022). "In normal cells, double-strand DNA breaks are repaired by homologous recombination; however, this repair mechanism is compromised in the presence of loss-of-function mutations in the tumour suppressor genes, BRCA1 and BRCA2." (PMID 34795408, 2022). "Subsequently, BRCA1 sequencing and CMA array on tumor DNA (sample estimated tumor infiltration – 20%) showed the BRCA1 c.3841C>T family variant with an AF of 43%, while the CMA was normal." (PMID 35280729, 2022). "For exploratory purposes, patients whose tumor contained a loss-of-function (LOF) mutation in at least one of the 18 HRR genes including BRCA1/2 were considered as HRRm." (PMID 36970052, 2022). "Patients with TNBC can also carry BRCA-1 gene mutations, showing BRCA-1 gene-deficient tumor gene expression profiles." (PMID 36278891, 2022). "Smaller tumor size is associated with better OS and less lymph node involvement in pT1 BRCA1/2-associated BC patients." (PMID 35507134, 2022). "This is the case for the synthetic lethality approach using PARPis in tumours with mutations in the BRCA1 or BRCA2 genes." (PMID 36139634, 2022). "Here, the authors sequence primary and recurrent tumours of BRCA1/2 mutation carriers, finding PARP1 amplifications, differential BRCA2 isoform usage, and discordant loss of heterozygosity that are associated with recurrence." (PMID 36344544, 2022). "This study identifies tumor genetic backgrounds where to expand the use of PARPis beyond mutations in BRCA1 or BRCA2." (PMID 36969741, 2022).
tumor (continued). "When C‐NHEJ reactions are inhibited, DNA lesions inflicted by pyridostatin in BRCA1/2‐deficient cells and tumours persist even after compound removal." (PMID 35107878, 2022). "Across all tumor types, 4.5% (n = 1422) of patients in our cohort had a germline pathogenic or somatic driver alteration in BRCA1/2." (PMID 36418296, 2022). "These genes have been associated with tumour suppression (BRCA1 and FAT1), DNA repair (POLE), morphogenesis (HOXD11), epigenetic regulation (WHSC1), lipid metabolism (PPARG) and red blood cell development (GATA1)." (PMID 36131292, 2022). "To gain a comprehensive understanding of tumor metastasis associated with Brca1 deficiency, we analyzed a cohort of 207 tumor-bearing Brca1-MSK mice and found that 47 mice (22%) developed metastasis in multiple organs." (PMID 35025764, 2022). "Typically, beyond 30% of HGSOC tumours are deficient in BRCA1/BRCA2 genes, via either germline or somatic mutations, or hyper-methylation." (PMID 36230510, 2022). "of the very same guidelines, it is stated that “Somatic tumor testing for BRCA1 and BRCA2 pathogenic or likely pathogenic variants should be performed in women who do not carry a germline pathogenic or likely pathogenic BRCA1/2 variant”." (PMID 35326583, 2022). "Presence of HR deficiencies such as BRCA1/2 mutations cause amplification of tumour mutational burden and contribute to immune checkpoint inhibitor sensitivity." (PMID 36010882, 2022). "This indicated that the recurrent tumor originated from a subclone that, early in its evolutionary history, had experienced BRCA1 deficiency in order to generate BRCA1-related genomic mutational signatures." (PMID 35857626, 2022). "Tumour acquired (somatic) mutations in BRCA1/2 genes have also been reported to occur in approximately 6–7% of cases." (PMID 35735457, 2022). "Our study provides further support for the expansion of tumour testing to include other HCP genes, as a higher proportion of non-BRCA1/2 variants detected in tumours were of germline origin." (PMID 36011309, 2022). "Although we did not detect known germline variants, likely due to low prevalence, we were able to identify 22 BRCA1 variants, which were more readily detected in evDNA across patients than in cfDNA (concordance with tumor for evDNA: 100% and cfDNA: 88.89%)." (PMID 35205822, 2022). "In this study, we report that pyridostatin is a compound suitable for in vivo use and has high specificity against BRCA1/2‐deficient tumours." (PMID 35107878, 2022). "For example, BRCA1 deficiency impairs stress-induced mitophagy and triggers inflammasome activation, creating a tumor-associated microenvironment, facilitating tumor proliferation and metastasis." (PMID 35440104, 2022). "Taking this information into account, a CMA and NGS of the tumor DNA (estimated tumor infiltration – 30%) were performed, identifying the known germline BRCA1 variant with an AF of 35% and an additional NM_004985.5(KRAS_v001):c.35G>A variant with an AF of 23%." (PMID 35280729, 2022). "The clinical efficacy of PARPi against BRCA1/2‐deficient tumours is limited by the rapid development of drug resistance." (PMID 35107878, 2022). "We did not observe any clustering associated with tumor origin (breast or ovarian), tumor type (primary or recurrent), or germline mutation (BRCA1 vs. BRCA2)." (PMID 36344544, 2022). "Lymph node involvement is a frequent occurrence in BRCA1/2-associated BC and increases with larger tumor size." (PMID 35507134, 2022). "Breast-cancer susceptibility gene 1 (BRCA1) is a major tumor-suppressor gene associated with several anti-carcinogenic pathways." (PMID 36193432, 2022).
tumor (continued). "Further strengthening the anti‐tumour activity of pyridostatin against PARPi‐resistant tumours is its inhibitory effect against BRCA1‐deleted PDTXs, which carry inactivating mutations in the REV7 (MAD2L2) gene." (PMID 35107878, 2022). "Of the 146 FFPE HGSC tumour specimens tested, 41 (28%) carried a Tier I/II variant in either BRCA1 or BRCA2 (n = 36), or BRCA1/2 plus a second variant (n = 5)." (PMID 36011309, 2022). "Our results with pyridostatin provide a strong rationale for testing it in combination with immune blockade drugs (e.g. anti‐PD‐1 or anti‐CTLA4 antibodies) for the treatment of BRCA1/2‐deficient tumours." (PMID 35107878, 2022). "One key result reported in our study is that pyridostatin restricts the growth of BRCA1/2‐deficient tumours that have become resistant to PARPi." (PMID 35107878, 2022). "Recognizing that non-BRCA1/2 variants still have clinical relevance, until tumour testing is expanded, germline testing cannot be replaced." (PMID 36011309, 2022). "The association between AKT groups and tumor BRCAness was partially supported by the results on the BRCA1/BRCA2 genetic testing, which was available for 36 patients." (PMID 35053468, 2022). "The five patients with pathogenic/likely pathogenic BRCA1/2 variants identified on tumor samples were addressed for genetic counseling and germline genetic testing." (PMID 36612041, 2022). "There are therefore theoretical concerns on potential increased radiation sensitivity of normal tissue among BRCA1 mutation carriers, but also potential increased effectiveness against tumours." (PMID 36010882, 2022). "This is the case when BRCA1/2 function is lost in homology‐directed repair (HR) deficient breast, ovarian, prostate, and pancreatic cancers, conferring the tumours' sensitivity to PARP inhibition via synthetic lethality." (PMID 35355264, 2022). "Our results indicate that EOC tumour testing can detect both BRCA1/2 Tier I/II and ACMG 1/2 variants." (PMID 36011309, 2022). "PARPis are specifically lethal to BRCA1/2‐deficient tumours because PARP1/2 enzymes, the targets of PARPi, bind to DNA ends." (PMID 35107878, 2022). "Our study found that tumor samples in the high-risk group expressed higher levels of BRCA1 and BRCA2 but lower levels of CTLA4 and PDCD1." (PMID 36704358, 2022). "Altogether, our results suggest that the G4 ligand pyridostatin is a compound suitable for targeting BRCA1/2‐deficient tumours and for overcoming PARPi resistance in vivo, thus highlighting its potential for therapeutic development." (PMID 35107878, 2022). "Targeted deletion or pharmaceutical inhibition of Tgfβr2 in Brca1-deficient tumor cells reduces EMT and suppresses tumorigenesis and metastasis." (PMID 35236825, 2022). "A recent study comparing BRCA1/2 variant status between germline and somatic testing results showed 100 percent concordance, providing validation for the use of tumour testing to the determine potential utility of treatment, as well as hereditary cancer risk." (PMID 36011309, 2022). "Tumor testing can be used to identify an additional 3%–9% of patients with somatic BRCA1/2 mutations besides germline mutations and thus can save time and cost by identifying all the potential patients who can benefit from PARP inhibitor therapy." (PMID 35813356, 2022). "The myChoice® CDx is the first and only FDA-approved tumor test that detects BRCA1/2 variants and/or scores HRD status." (PMID 35626108, 2022). "When stratified by BRCA1/2 mutation, a similar OS was seen for the different tumor sizes, except for pT1b (97.4% 10-year OS in BRCA1 vs 82.8% in BRCA2,p = 0.049)." (PMID 35507134, 2022). "This is a unique example of genomic plasticity that is caused by the treatment of BRCA1-deficient tumors, but it can lead to tumor regeneration." (PMID 35300412, 2022).
tumor (continued). "The non-BRCA1/2 tumour cohort showed that 7/8 (87.5%) were of germline variant origin and 1/8 (12.5%) was a somatic event." (PMID 36011309, 2022). "Our results suggest that MAD1L1 is a tumor suppressor in the context of BRCA1/2 mutation-associated tumors, loss of which is associated with recurrent disease." (PMID 36344544, 2022). "Consistent with this, chemical inhibitors of DNA‐PKcs, a core component of C‐NHEJ kinase activity, act synergistically with pyridostatin in eliminating BRCA1/2‐deficient cells and tumours." (PMID 35107878, 2022). "The best-studied trial for targeted cancer therapies that exploits this principle is the use of poly-ADP ribose polymerase (PARP) inhibitor against tumor with breast cancer gene 1 (BRCA1) or 2 (BRCA2) mutations." (PMID 35203541, 2022). "Our findings highlight the chemotherapeutic potential of pyridostatin/NU‐7441/paclitaxel combination to treat BRCA1/2‐deficient tumours." (PMID 35107878, 2022). "Loss of WT of a germline BRCA1 variant in the tumor predicts pathogenicity with a sensitivity of 65% and specificity of 78%." (PMID 35039532, 2022). "Germline mutations in BRCA1 or BRCA2 tumor suppressor genes, which play important roles in homologous recombination, are found in approximately 10% of cases of epithelial OC." (PMID 36509287, 2022). "SMARCAL1, a chromatin remodeling complex depletion, reduces the sensitivity of tumor cells deficient in BRCA1/2 and causes PARP inhibitor resistance, however, this effect appears to be cell-type specific." (PMID 35873570, 2022). "DNA replication and repair defects caused by loss of BRCA1/2 can be exploited therapeutically to specifically target tumours carrying mutations in these genes." (PMID 35107878, 2022). "Compounds that bind and stabilise G4s have been shown to be active against BRCA1/2‐deficient xenograft tumours established in mice (RHPS4 and CX‐5461)." (PMID 35107878, 2022). "Another mechanism of PARPi resistance in BRCA1/2-deficient tumor cells is due to the downregulation of PARP1 expression, thereby resulting in PARylation-independent cell proliferation and/or the inefficiency of PARP1 trapping by PARPi." (PMID 36497275, 2022). "The researchers used targeted NGS to first screen tumour samples for germline BRCA1/2 mutation or reversion status before analyzing cfDNA." (PMID 35545786, 2022). "HR-deficiency is a molecular variation of genome instability, which is defined as carriers of BRCA1/2 mutations or tumor genomic instability (HRD score ≥42)." (PMID 35281113, 2022). "The DDIR signature was developed using microarray data from BRCA1/2-deficient, DNA-repair-deficient tumours with the specific aim of identifying such tumours." (PMID 34728791, 2022). "A pathogenic variant was detected in 41.1% (60/146) of tumours tested, with 68.3% (41/60) having either a BRCA1 or BRCA2 variant (n = 36), or BRCA1/2 plus a second variant (n = 5), and 31.2% (19/60) carrying a pathogenic variant in another HCP gene." (PMID 36011309, 2022). "BRCA1 is a tumor suppressor gene encoding a large protein that coordinates several cellular pathways including DNA repair, transcriptional regulation, cell-cycle control, centrosome duplication, and apoptosis." (PMID 35280729, 2022). "Among these tumors was one bi-allelic BRCA deficient tumor with a somatic BRCA1/2 mutation (M096)), three harbored a BRCA VUS and eleven tumors were BRCA wild-type." (PMID 35662281, 2022). "More investigations are warranted to examine the direct relationship between iNOS/NO, BRCA1/2 mutations, and the onset of tumor development." (PMID 35740092, 2022). "Whilst the tumour characteristics tested were significantly associated with BRCA1 status, these were also associated with BRCA2 status, with the exception of ER, PR, HR, and TNBC." (PMID 35143328, 2022). "The assay was developed using DNA microarray data from patients with FA and from breast tumours (enriched for BRCA1/2-mutant-associated tumours)." (PMID 34728791, 2022).
tumor (continued). "Even after adjusting for other characteristics (lymph node status and tumor grade), BRCA1 mutation status remained an independent significant predictor of pCR." (PMID 36230495, 2022). "The working model of this process is that cytotoxic chemotherapy induces the specific demethylation of one BRCA1 promoter allele in a stochastic fashion in subpopulations of cells within a tumor." (PMID 35857626, 2022). "In the case of PARPi, the ability to activate immune responses directly correlates with their anti‐tumour activity, as highlighted in pre‐clinical models of BRCA1‐deficient ovarian and triple negative breast tumours." (PMID 35107878, 2022). "As well, a further suggestive association towards a lower ERα/ERβ1 ratio in BRCA1/2-mut-carrier tumours was observed (p = 0.06, in both cases)." (PMID 36230510, 2022). "Increased BRCA1/2 variants are frequent in triple-negative tumors, a tumor type associated with the presence of germline BRCA1 variants." (PMID 35875117, 2022). "As a control, we used the PARPi talazoparib, known for its ability to eradicate BRCA1/2‐deficient tumours in mice and recently licensed for use in metastatic breast cancer patients carrying BRCA1/2 germline mutations." (PMID 35107878, 2022). "BRCA1 is a tumor suppressor gene that encodes for a DNA repair protein involved in double-strand break (DSB) repair." (PMID 36346676, 2022). "In other words, the associations between high BRCA1 expression and aggressive tumor behavior (poor DMFS) were consistently revealed within the tamoxifen-treated patients and within each of two other datasets of patients who did not receive tamoxifen treatment." (PMID 34996912, 2022). "BRCA1, a tumor suppressor associated with the development of breast, and ovarian, participate in multiple biological pathways including the DNA damage response, transcriptional control, cell growth, and apoptosis." (PMID 36523600, 2022). "Consistently, c-olaparib and c-rucaparib pull downs using frozen BRCA1-deficient OC tumor samples in comparison with BRCA1-proficient OC tumor samples, also showed increased enrichment of Ku70/Ku80 in BRCA1-deficient samples." (PMID 36183837, 2022). "In BRCA1-deficient tumor cells, DYNLL1 promotes 53BP1 oligomerization to stimulate NHEJ, and through its interaction with MRE11 Inhibition of DNA end excision, the combination of these two effects leads to genomic instability." (PMID 36091750, 2022). "The subgroup of patients with either germline (inherited) or somatic (tumour acquired) BRCA1/2 mutations derive the greatest benefit from PARP inhibitors." (PMID 35735457, 2022). "As reported by others, and reiterated in our study, tumour testing for BRCA1/2 variants is a robust way to triage patients with BRCA1/2 variants, not only for PARPi therapy, but possibly also for genetic counselling." (PMID 36011309, 2022). "Concomitant driver mutations included activating mutations in classic oncogenes (e.g., KRAS, NRAS, EGFR, and PIK3CA), as well as loss-of-function mutations in tumor suppressors (e.g., BRCA1/2 and PTEN)." (PMID 36369474, 2022). "Accumulation of replication‐associated DNA damage is characteristic of BRCA1/2‐mutated tumours and increases their vulnerability to targeted therapies, with inhibitors of poly(ADP‐ribose) polymerases (PARPs) as a prominent example." (PMID 35107878, 2022). "The clinical validation of F1CDx was based on a clinical bridging retrospective analysis of 368 patients included in SOLO1 whose tumor samples were available for analysis, of which 313 patients were determined to have a documented mutation in BRCA1/2 by F1CDx." (PMID 35294956, 2022). "Analysis of xenograft tumor growth derived from BRCA1-mutated and BRCA1-wildtype TNBC cell lines showed that co-treatment with selinexor and olaparib had a synergistic effect on tumor inhibition as compared to selinexor or olaparib alone." (PMID 34504648, 2021).